ADIPOQ (adiponectin, C1Q and collagen domain containing)
Diseases named in the same sentence as ADIPOQ in open-access papers (continued):
Sharing a sentence is not in itself a finding about the gene and the disease.
Obesity (continued). "No other ADIPOQ variants showed significant association with obesity in our population, underscoring rs1501299 and rs3774261 as key genetic determinants of obesity in the Tunisian population." (PMID 41598180, 2025). "Concurrent overweight/obesity and hypertension could modify the activity of the adiponectin gene, ADIPOQ, a gene that is related to energy and lipoprotein metabolism, and influence disease development." (PMID 35055468, 2022). "ADIPOQ and IGFBP2 were reported before to be associated with T2D and obesity." (PMID 34016094, 2021). "ADIPOQ is relevant in obesity and may potentially lead to metabolic syndrome, thus possibly worsening the prognosis of MIBC patients." (PMID 33465047, 2021). "Moreover, studies have also reported altered ADIPOQ methylation in the placenta of pregnant women with obesity and GDM." (PMID 33750967, 2021). "In addition, five related genes of obesity (ADIPOQ, GCG, PCSK1N, TFAP2A, and PYY) were distributed in the top 25 over/underexpressed genes of cancer tissues." (PMID 33299884, 2020). "In conclusion, our data suggest blunted ADIPOQ signaling in obesity, may – besides its established impact on insulin signaling – further deteriorate metabolic function via circadian disruption of central metabolic control circuits." (PMID 32644041, 2020). "Because the genetic variants of the ADIPOQ gene in different racial populations were associated with PCOS, this gene may be a risk factor for obesity and insulin resistance of PCOS." (PMID 32133054, 2019). "Interestingly, the results of this meta-analysis suggested that polymorphisms in the adipokine genes, ADIPOQ, IL-1β, IL-6, and TNF-α, increase the risk of obesity." (PMID 31354816, 2019). "Our results are consistent with three studies in Mexican children that showed no contribution of several polymorphisms in ADIPOQ gene (rs2241766, rs182052, rs266729, and rs822393) in children obesity." (PMID 31354816, 2019). "Successively, we analysed the genotype of the ADIPOQ gene in both normal weight and people with severe obesity, finding a significant difference in the distribution of 3 polymorphisms within the population with obesity (rs17300539 c.11391G>A, rs60806105 c.11156insCA, rs1501299 c.214+62G>T)." (PMID 31547312, 2019). "The expression of circulatory AdipoQ is decreased in obesity and diabetes." (PMID 30567565, 2018). "Surprisingly, adipoQ expression was significantly increased by obesity in this depot." (PMID 28145500, 2017). "In some studies, functional SNPs in ADIPOQ were found to have a significant effect on human body composition, but other reports did not confirm an association between these polymorphisms and obesity." (PMID 27240401, 2016). "We next examined whether obesity and adipose tissue distribution alter the regulation of ADIPOQ gene expression in different adipose tissue depots." (PMID 26838789, 2016). "Considering the close relationship between ADIPOQ +45 T > G and the typical components of MS as well as the many resulting potential disease risks such as obesity, cancer, and hypertension, we summarized data from the published meta-analyses as well as the primary meta-analysis in our study." (PMID 27578536, 2016). "We have thus hypothesized that LEP and ADIPOQ DNA methylation changes might be involved in obesity development and its related complications." (PMID 25929254, 2015). "As epigenetic alterations in AT may be associated with obesity-related phenotypes, we performed quantitative analysis of single CpG methylation within the LPL, ADIPOQ and PPARγ promoters." (PMID 26148147, 2015). "Altogether these results suggest that LEP and ADIPOQ DNA methylation profiles might be involved in the pathology of obesity and cardiometabolic diseases." (PMID 25929254, 2015). "Accordingly, we hypothesized that decreased LEP DNA methylation and increased ADIPOQ DNA methylation in adipose tissue could lead to higher degree of obesity and pro-inflammatory state, dyslipidemia, hypertension and insulin resistance." (PMID 25929254, 2015).
Obesity (continued). "Henceforth, the objective of this study was to determine whether LEP and ADIPOQ DNA methylation levels in subcutaneous (SAT) and visceral (VAT) adipose tissues were associated with obesity and obesity-related complications severely obese men and women." (PMID 25929254, 2015). "Nevertheless, LEP and ADIPOQ epigenetic profiles in adipose tissue and their associations with obesity and obesity-associated metabolic perturbations have not been assessed so far." (PMID 25929254, 2015). "Levels of ADIPOQ have been inversely correlated with obesity." (PMID 25923423, 2015). "Whether ADIPOQ epigenetic profile in SAT is established before or after the onset of obesity will need to be confirmed, but is clearly of strong interest." (PMID 25929254, 2015). "Furthermore, the pharmacological activation of PPARγ was found to induce ADIPOQ expression to regulate glucose metabolism in obesity." (PMID 25093444, 2014). "Interestingly, persons without family history of diabetes revealed stark correlation of rs2241766 SNP, obesity, and insulin sensitivity among German people, making the role of ADIPOQ gene in T2DM controversial." (PMID 25121131, 2014). "Therefore, additional studies warrant validation of the relationship between the ADIPOQ gene and obesity identified in this study." (PMID 21603224, 2011). "Given the association between metabolic syndrome traits and colorectal cancer risk and the key role of ADIPOQ and its receptor genes in the development of obesity and insulin resistance, emerging interest was focused on the role of ADIPOQ and its receptor genes in colorectal carcinogenesis." (PMID 22087284, 2011). "It was previously demonstrated that the genetic effects of variants associated with either insulin secretion (like for GCK, KCNJ11 or TCF7L2) or insulin action (for ENPP1, ADIPOQ or PPARG) may be modulated by the obesity status or adiposity." (PMID 19368707, 2009). "This large case-control study further supports the hypothesis that the T2D risk contribution of ENPP1, ADIPOQ, PPARG and TCF7L2 SNPs may be modulated by obesity status." (PMID 18498634, 2008). "ENPP1, ADIPOQ, PPARG and TCF7L2 single nucleotide polymorphisms (SNPs) have previously been associated with T2D and have shown variable significance amongst different classes of obesity." (PMID 18498634, 2008). "Adiponectin (ADIPOQ), a representative adipokine, has several functions, including preventing fatty acid oxidation and inflammation, promoting blood glucose uptake by counteracting insulin resistance, and inhibiting atherosclerosis, thereby preventing obesity-related pathological states." (PMID 38822022, 2024). "Considering the weight-promoting effects of rest phase food intake and the therapeutic potential of time-restricted eating for diet-induced obesity, we speculated that timed activation of hypothalamic ADIPOQ signaling may improve body weight regulation under obesogenic conditions." (PMID 32644041, 2020). "Therefore, this article presents recent studies about AdipoQ on obesity-related AD." (PMID 33584324, 2020). "ADIPOQ is known to have decreased levels in conditions such as T2DM, obesity, and heart disease, implicating its importance in the metabolic homoeostasis." (PMID 38918595, 2024). "It is thus possible that AdipoQ-LPL mice increase these or other factors such as lipids or metabolites that, in turn, affect β-cell function in the setting of HFD-induced obesity." (PMID 36566329, 2022). "They reported that adipogenic and insulin signaling genes (CEBPB, PPARG, ADIPOQ, IRS-1, IRS-2, GLUT4, among others) were downregulated in obesity." (PMID 36432612, 2022). "Obesity and metabolism-related genotypes were also assessed by 10 studies, including FTO, UCP1, MC4R, and ADIPOQ." (PMID 36235756, 2022). "Evaluated genotypes also included those relating to cardiovascular health (ACE), obesity and metabolism-related genotypes (FTO, UCP1, MC4R, and ADIPOQ), sweet taste perception (Tas1R2 and KCTD10), and endurance (GDF5)." (PMID 36235756, 2022).
Obesity (continued). "APN (also known as Acrp30, AdipoQ, GBP-28, and apM1) is the most abundant peptide secreted by adipocytes, and plays a central role in obesity-related diseases." (PMID 36380279, 2022). "It is pertinent to note that out of the total 10 obesity related SNPs from FTO, ADIPOQ and LEPR genes considered in this study, seven were involved in pair-wise interactions and associated with either risk or protective nature towards manifestation of T2DM." (PMID 34784930, 2021). "ADIPOQ, FTOTGFβ, and DENND1A as the main obesity- and chronic inflammation-related genes have roles in PCOS pathophysiology." (PMID 32133054, 2019). "Several of the observed DMCs were located in genes related to T2D or obesity, such as ALOX12, PAMR1, and GNAS in WB; IRS1, LEP, and ADIPOQ in SAT; LCAT, FOXA2, KCNQ1, and GCKR in VAT; and PKD4, HNF4A, XBP1, and PON1 in LT." (PMID 29466957, 2018). "On day 4, the network showed inhibition of the upstream regulator N-CoR in BPS-treated cells which leads to activation of adipogenic genes such as SCD, PLIN1, ACACB, CIDEC, ADIPOQ and FABP, leading to obesity." (PMID 27685785, 2016). "The variants of genes like PPARG, ADIPOQ, and ENPP1 which act at the level of insulin resistance have been shown to increase the risk of T2DM only in obese populations and hence it has been suggested that T2DM risk contribution of gene polymorphism may be modulated by obesity status." (PMID 26491214, 2015). "To determine whether LEP and ADIPOQ epigenetic profiles are involved in the pathogenesis of obesity and cardiometabolic complications, we first assessed the associations between LEP and ADIPOQ DNA methylation levels in adipose tissues and blood and obesity-related anthropometric measures." (PMID 25929254, 2015). "MCR1/CD68 ratio increased significantly after weight loss in parallel to adipogenic genes, such as FASN, ADIPOQ, IRS1 and SLC2A4, whereas LEP (an obesity gene marker) and IL6 (an inflammatory marker) decreased." (PMID 23951013, 2013). "Besides, the ADIPOR1 rs1539355 could highlight the role of ADIPOQ SNPs in obesity genotype." (PMID 22087284, 2011). "We hypothesized that breast tumor tissue has higher ADIPOQ and ADIPOR1 levels compared to adjacent adipose tissue in postmenopausal women with obesity versus those with a normal BMI." (PMID 41456223, 2025). "We hypothesized that the tumour microenvironment (TME) of the breast had lower levels of ADIPOQ and ADIPOR1 in postmenopausal women with obesity than in those with a normal BMI." (PMID 41456223, 2025). "However, its role in the development of human obesity requires further investigation since in human VAT, miR-378 levels correlated positively with ADIPOQ expression." (PMID 34943849, 2021). "We found that the intronic +276G > T SNP of the ADIPOQ gene did not correlate with plasma adiponectin levels or obesity." (PMID 34208364, 2021). "The reduction of adiponectin mRNA expression in response to obesity might be regulated by the obesity regulatory element (ORE) sites; two of these were identified in the promoter region of the human ADIPOQ gene." (PMID 34208364, 2021). "We observed positive correlations between the amount of mtDNA and expression level of the ADIPOQ gene in the SAT in patients without T2DM (with grade I obesity), which was confirmed in the study data." (PMID 30871547, 2019). "The biological processes “Platelet degranulation,” “Positive regulation of glucose import” and “Cellular response to insulin stimulus,” already found modulated in obesity (PDGFB, SERPING1 ADIPOQ, PIK3R1, IGF1) were further enriched in ObCRC with respect to Ob individuals." (PMID 30838002, 2019). "A meta-analysis of the influence of adipokine polymorphisms in adipokine genes (LEP, ADIPOQ, IL-1β, IL-6, and TNF-α) in obesity susceptibility showed that there was not association with the risk of obesity and LEP variants in adults." (PMID 31354816, 2019).
Obesity (continued). "Most of the studied effects of AdipoQ in relation to many health conditions, including CHD, stroke, diabetes, obesity, myocardial infarction (MI) and other CVDs, are related to the circulating levels and effects of adiponectin – the protein encoded by the AdipoQ gene." (PMID 26754433, 2016). "This metabolically-healthy obese population has a unique obesity phenotype and metabolism, and LEP and ADIPOQ DNA methylation profiles might be distinct in these participants." (PMID 25929254, 2015). "The associations of 23 SNPs located within 17 candidate genes (MTHFR, PPARγ, LPL, INSIG, TCF7L2, FTO, KCNJ11, JAZF1, CDKN2A/B, ADIPOQ, WFS1, CDKAL1, IGF2BP2, KCNQ1, MTNR1B, IRS1, ACE) with overweight and obesity, diabetes, metabolic phenotypes, and MetS were examined in both studies." (PMID 24959828, 2014). "To study the roles of L-PGDS and PGD2 in obesity, we generated the experimental mice by breeding the L-PGDSflox/flox mice with either of two distinct types of adipose-specific L-PGDS gene knockout (KO) mice: aP2-Cre/L-PGDSflox/flox and AdipoQ-Cre/L-PGDSflox/flox mice." (PMID 30760783, 2019). "Thus the neuroprotective role of AdipoQ takes part in the regulation of brain inflammation; it was proposed that the lack of AdipoQ in obesity might induce neuroinflammation leading to AD and other dementias." (PMID 33584324, 2020). "Positive correlations were also observed between mtDNA copy number and the expression level of the ADIPOQ gene (r = 1.0, p < 0.01) in SAT in patients without T2DM (with grade I obesity)." (PMID 30871547, 2019).
Insulin resistance (71 papers, 2006 to 2025). Increased resistance towards insulin, that is, diminished effectiveness of insulin in reducing blood glucose levels. "Similar associations between the rs1501299 variant in the ADIPOQ gene and insulin resistance, as well as susceptibility to T2DM, have been documented in various ethnic groups." (PMID 40454209, 2025). "The rs1501299 is one of the polymorphisms in the ADIPOQ gene (SNP276) at position 276 is associated with insulin resistance and T2DM in the Saudi population." (PMID 40454209, 2025). "The ADIPOQ gene, implicated in diabetes development, is examined for the rs1501299 polymorphism, known for its associations with insulin resistance and T2DM in various populations." (PMID 40454209, 2025). "Several studies have associated the presence of ADIPOQ gene polymorphisms with insulin resistance, adiponectin levels, and metabolic diseases such as diabetes, although with varying degrees of correlation depending on ethnicity." (PMID 37953238, 2023). "Low levels of adiponectin, as observed in AdipoQ knockout mice or in patients affected by type 2 diabetes, have been associated with insulin resistance in diabetes." (PMID 35250480, 2022). "Several reports investigated the association of rs2241766 of the ADIPOQ gene with several metabolic disorders believed to be predisposed by insulin resistance." (PMID 35528179, 2022). "For example, ADIPOQ/adiponectin stimulates autophagy and reduces insulin resistance caused by high-fat diet (HFD)." (PMID 34829881, 2021). "In contrast, AdipoQ was found to enhance insulin susceptibility in the SH-SY5Y neuroblastoma cell line exhibiting insulin resistance, via AdipoQR1 initiation of AMPK." (PMID 33584324, 2020). "ADIPOQ or adiponcetin is an important hormone from adipocyte, whose reduction in secretion causes insulin resistance." (PMID 29201145, 2017). "In the present study, we evaluated the association between 4 insulin resistance genes (ADIPOQ, LEPR, RETN, and TRIB3) and both T2DM and hypertension." (PMID 24414038, 2014). "Polymorphisms of ADIPOQ are linked with metabolic syndromes: for example, insulin resistance, abdominal obesity, impaired glucose tolerance, dyslipidemia, hypertension, increased fasting glucose, and plasma adiponectin level." (PMID 25121131, 2014). "ADIPOQ methylation has been associated with insulin resistance and other metabolic parameters." (PMID 41007833, 2025). "From a pathophysiological point of view, insulin resistance is considered the main defect of metabolic syndrome and ADIPOQ gene variants could be involved in this susceptibility." (PMID 38140287, 2023). "And ADIPOQ deficiency might lead to insulin resistance and NAFLD by mediating the AMPK signaling pathway." (PMID 36712867, 2022). "Single nucleotide polymorphisms (SNPs) in obesity-related genes, such as ectonucleotide pyrophosphatase phosphodiesterase 1 (ENPP1) and adiponectin (ADIPOQ), potentially increase the risk of insulin resistance, the most common metabolic dysregulation related to obesity." (PMID 34208364, 2021). "Other studies suggested that insulin resistance is associated with an excess of adiposity induced by high free fatty acid and lower levels of plasma AdipoQ." (PMID 33584324, 2020). "Another important adipokine, Adiponectin (also known as AdipoQ), contributes to enhance insulin sensitivity in obese mouse, normalize lipid metabolism dysfunction, inhibit energy expenditure and lead to weight loss in diet-induced insulin-resistance mice." (PMID 27223282, 2016). "Since GDM is a multifactorial condition, we also evaluated the correlation of ADIPOQ gene SNPs with the clinical characteristics of participants, such as lipid profile, glucose parameters, and insulin resistance." (PMID 37953238, 2023). "Genetic studies have established a link between ADIPOQ and insulin resistance as well as its role in the pathogenesis of T2DM." (PMID 37238960, 2023).